PRMT5 (protein arginine methyltransferase 5)
Diseases named in the same sentence as PRMT5 in open-access papers (continued):
Sharing a sentence is not in itself a finding about the gene and the disease.
glioblastoma (continued). "Many studies have identified that increased activity and upregulation of PRMT5 is a key regulator of cancer progression and marker for poor prognosis in multiple malignancies, including breast, gastric, glioblastoma, leukaemia, lung, lymphoma, ovarian, pancreatic and prostate cancer." (PMID 37795443, 2023). "In addition, the PRMT5 inhibitor induced antitumor effects in glioblastoma patient-derived xenografts." (PMID 37342192, 2023). "In addition, FAK and PRMT5 regulates the metabolic shift in glioblastoma cells plated on osteopontin." (PMID 33807786, 2021). "Based on differential gene expression analysis, the mechanistic effect of PRMT5 inhibition in glioblastoma may be related to PRMT5 induced altered expression of genes associated with cell regulation." (PMID 34680285, 2021). "Finally, a recent paper by Holmes and colleagues explored possible synergies between PRMT5 inhibition and other treatments in glioblastoma." (PMID 33404912, 2021). "PRMT5 regulates the PETN-Akt axis in glioblastoma cell lines (GBM)." (PMID 33670008, 2021). "In glioblastoma, PRMT5 could regulate PTEN expression and induce the activation of Akt and ERK, components of a pathway that could regulate aerobic glycolysis." (PMID 30922330, 2019). "Recent studies found PRMT5 as a key epigenetic regulator in glioblastoma tumorigenesis." (PMID 31694585, 2019). "Furthermore, PRMT5 over-expression occurs in glioblastoma, leukemia, lung, ovarian, and prostate cancer and lymphoma." (PMID 24098663, 2013). "Herein we describe the discovery of TNG456, a potent and highly selective MTA-cooperative PRMT5 inhibitor that is brain penetrant in preclinical species and currently in Phase I/II clinical studies for the treatment of advanced or metastatic solid tumors with MTAP loss, with a focus on glioblastoma." (PMID 42150143, 2026). "Given its involvements in splicing regulation in normal neuronal and haematopoietic stem cells, and its recently reported contribution to splicing in glioblastoma stem cells (GSCs), we hypothesised that PRMT5 mediates chemoresistance in BCSCs through RNA splicing mechanisms." (PMID 39695328, 2025). "Notably, PRMT5 is overexpressed in a number of cancers, including melanoma, multiple myeloma, lymphoma, glioblastoma, breast, lung, pancreas, prostate, ovarian, and colorectal cancers, and high expression of PRMT5 often correlates with poor patient clinical outcomes." (PMID 38136401, 2023). "PRMT5 inhibition or depletion suppresses glioblastoma (GBM) growth by impairing removal of retained introns in genes functioning in cell proliferation, anti-senescence and anti-apoptosis." (PMID 32743345, 2020). "However, the mechanistic role of PRMT5 in treatment-resistant glioblastoma is unknown." (PMID 41986321, 2026). "While we were the first to evaluate combination therapy with PRMT5 inhibition and trametinib, investigators have been examining the use of various combination therapies in conjunction with MEK inhibitors for glioblastoma therapy." (PMID 40725122, 2025). "With the inhibition of PRMT5, TMZ-induced RAD51 was subdued suggesting the role of PRMT5 in HR in the context of glioblastoma." (PMID 39989968, 2025). "However, the mechanistic role of PRMT5 in glioblastoma therapy resistance is unknown." (PMID 39989968, 2025). "Genes such as VEGFA, PD-L1, PIK3CD, PRMT5, and STAT3 emerge as central nodes driving glioblastoma progression and therapeutic resistance." (PMID 41179304, 2025). "As TMZ is the first-line chemotherapeutic agent in treating glioblastoma, this study has significant clinical application to overcome TMZ resistance as LLY-283 is a potent brain penetrant PRMT5 inhibitor." (PMID 39989968, 2025). "This is the first study to test the effect of concomitant inhibition of PRMT5 and TMZ treatment in glioblastoma models." (PMID 39989968, 2025).
glioblastoma (continued). "Patient-derived primary glioblastoma neurospheres (GBMNS), treated with PRMT5 inhibitor (LLY-283) or transfected with PRMT5 target-specific siRNA were treated with TMZ and subjected to in vitro functional and mechanistic studies." (PMID 39989968, 2025). "For instance, in glioblastoma (GBM), pharmacological inhibitors of PRMT5 have been shown to reduce the proliferation of GBM stem cells and enhance the sensitivity of proneural subpopulations by altering the splicing patterns of cell-cycle related gene products." (PMID 39678513, 2024). "In glioblastoma models, one study found PTEN as a downstream target of the type II arginine methyltransferase, PRMT5." (PMID 38183103, 2024). "The PD properties of NTG908 allow for PRMT5 inhibition, which was confirmed by decreased levels of SDMA-modified proteins in a dose-dependent manner in a glioblastoma xenograft model." (PMID 38136401, 2023). "In addition, a phase II clinical trial of LB100 (NCT03027388) showed an anti-glioblastoma (GBM) effect from LB100 in combination with PRMT5 inhibition." (PMID 37373360, 2023). "We have previously shown that protein arginine methyltransferase 5 (PRMT5) expression correlates with grade in malignant glioma, and PRMT5 knockdown decreased glycolysis and increased OXPHOS in glioblastoma cells." (PMID 33807786, 2021). "Pharmacological inhibition of focal adhesion kinase (FAK) or downregulation of protein arginine methyltransferase 5 (PRMT5) blocks metabolic shift toward glycolysis and inhibits glioblastoma cell migration and invasion." (PMID 33807786, 2021). "Patients with a higher expression level of PRMT5 had a worse prognosis for BLCA, head and neck squamous cell carcinoma (HNSC), LIHC, and SARC but a better prognosis for glioblastoma multiforme (GBM) and KIRC." (PMID 34933446, 2021). "Our finding is in according to a recent study elucidating that PRMT5 mediates the activation of Akt and ERK in glioblastoma neurosphere cells by regulating PTEN expression and ultimately participates in cellular senescence." (PMID 32023548, 2020). "Here we show that Myc/PRMT5 protein complex includes PRMT1, in both HEK293T and glioblastoma stem cells (GSCs)." (PMID 31685892, 2019). "In this study in the context of glioblastoma, our results show a negative correlation between PRMT5 inhibition and DNA repair pathways, thus reconfirming the pivotal role played by PRMT5 in DNA damage repair machinery." (PMID 39989968, 2025). "Concomitant treatment of LLY-283 and TMZ has significantly greater antitumor efficacy, suggesting that PRMT5 inhibition and TMZ combination could be a new therapeutic strategy for glioblastoma." (PMID 39989968, 2025). "In this study, we show that PRMT5 inhibition suppresses HR repair of glioblastoma, leading to increased TMZ-induced DNA damage, and enhances the antitumor efficacy in both in vitro and in vivo glioblastoma tumor models." (PMID 39989968, 2025). "Indeed, the combination of the PRMT5 inhibitor, JNJ-64619178, and trametinib in glioblastoma displayed an increase in the number of apoptotic cells and number of cells in G1 cell cycle arrest than either individual therapy alone." (PMID 38827317, 2024). "Here, PRMT5 expression was enriched at the promotor region of PTEN in glioblastoma neurospheres but not in the differentiated glioblastoma counterpart." (PMID 38183103, 2024). "EZH2 has been shown to be regulated by PRMT1, CARM1, and PRMT5, while whether PRMT6 is a regulator of EZH2 in glioblastoma is the subject of further investigation." (PMID 39043634, 2024). "Likewise, the combination of the PRMT5 inhibitor and LB100 (a protein phosphatase 2A (PP2A) inhibitor) enhanced G1 cell cycle arrest in glioblastoma cells." (PMID 39703687, 2024). "An active, but no longer recruiting phase I clinical trial is investigation PRT811, a PRMT5 inhibitor, but again without a glioblastoma focus as the trial is treating all high grade gliomas (clinicaltrials.gov)." (PMID 37205197, 2023).
glioblastoma (continued). "Whilst reduction in PTEN activity through promoter suppression by PRMT5 can lead to an alternative mechanism of upregulation of this axis in glioblastoma, the same is not observed in PDAC, lung cancer and gastric cancer." (PMID 34680285, 2021). "Interestingly, a recent work on glioblastoma primary cells highlighted a new level of PTEN expression control, focusing on the role of the protein arginine methyltransferase-5 (PRMT5) on self-renewal and proliferation of neurospheres." (PMID 31366089, 2019). "Therefore, we performed immunoprecipitation experiments, both in glioblastoma and HEK293T cells, to assess PRMT5 recruitment by Myc and Omomyc." (PMID 26563484, 2015). "In IDH-wildtype glioblastoma, the production of 2-HG is absent, allowing for PRMT5 evolution." (PMID 38827324, 2024). "Our collaborative group has developed a series of first-in-class small molecule inhibitors of PRMT5 (HLCL65, C220, PRT382, PRT543) demonstrating antitumor activity in MCL, DLBCL, HTLV-1 induced adult T-cell leukemia/lymphoma, acute myeloid leukemia (AML), and glioblastoma cells." (PMID 33989303, 2021). "While the Type II arginine methyltransferase, Protein arginine methyltransferase 5 (PRMT5), through symmetric di-methylation of histone and non-histone protein arginine proteins, regulates numerous cellular functions, its expression is dysregulated in glioblastoma." (PMID 39989968, 2025). "A recent report demonstrated that two orthogonal PRMT5 inhibitors, GSK3203591 and LLY-283, could inhibit the proliferation and self-renewal of glioblastoma (GBM) stem cells." (PMID 39885614, 2025). "However, given that the response to PRMT5 inhibitor therapy is partially dependent on molecular contexts such as MTAP deletion or altered splicing as seen in glioblastoma, its mechanism may not be tissue-specific but molecularly defined." (PMID 34680285, 2021). "PRMT5 gene dysregulation can occur in IDH-mutant WHO-G4 astrocytomas and IDH-wildtype glioblastomas, regardless of MGMT-promoter status." (PMID 38827324, 2024).
lymphoma (74 papers, 2009 to 2026). A malignant (clonal) proliferation of B- lymphocytes or T- lymphocytes which involves the lymph nodes, bone marrow and/or extranodal sites. "Aberrant expression of PRMT5 is associated with many cancer types such as lymphoma, leukemia, gastric carcinoma and testicular tumors." (PMID 19521535, 2009). "Furthermore, because PRMT5 has been demonstrated to play crucial roles in leukemia and lymphoma treatment, administration of EPZ015666 caused apoptosis in adult T-cell leukemia/lymphoma cell lines." (PMID 39826691, 2025). "Also, PRMT5 is particularly noteworthy for its association with lymphoma, leukemia, and acute myeloid leukemia (AML)." (PMID 39826691, 2025). "PRMT5 inhibition sensitizes lymphoma cells to ferroptosis inducers such as dimethyl fumarate (DMF), an electrophile that irreversibly depletes GSH via succination." (PMID 41998301, 2026). "We summarize the current state of development for inhibitors against Menin‐KMT2A, DOT1L, KDM1A, and Polycomb complexes, and the arginine methyltransferase PRMT5 for the treatment of myeloid malignancies, lymphoma, and different solid tumors." (PMID 40181550, 2026). "In leukemia and lymphoma, PRMT5 silences RB family members (RB1, RBL1, and RBL2) via hypermethylation of H3R8 and H4R3, thereby disabling RB-mediated cell cycle control and promoting proliferation." (PMID 41204384, 2025). "A recent study has shown that in leukemia and lymphoma, PRMT5 also controls mRNA expression of TIP60 and other DNA repair genes by regulating alternative splicing." (PMID 40735501, 2025). "In several lymphomas, PRMT5 acts synergistically with key tumorigenic drivers, including cyclin D1, c-Myc, and NOTCH1, to regulate the lymphomagenic process." (PMID 41154773, 2025). "For example, overexpression of protein arginine methyltransferase 5 (PRMT5) in lymphoma has been proposed as a potential contributor to increased SDMA in dogs." (PMID 40123416, 2025). "This is also associated with miRNA regulation, and it has been demonstrated that PRMT5 promotes lymphoma by increasing cyclin D1 and c-Myc expression through inhibition of miR-33b, miR-96, and miR-503." (PMID 41154773, 2025). "In leukemia and lymphoma cells, by methylation of the promoter region, PRMT5 induced silence of tumor suppressors Rb and enhanced proliferation." (PMID 40384988, 2025). "The methylation of Sm proteins through PRMT5 has been shown to ensure splicing fidelity in MYC-driven lymphomas, where the expression of these proteins are up-regulated." (PMID 38049564, 2024). "Previous studies revealed an oncogenic activity of the overexpressed PRMTs in distinct hematological malignancies, including AML (CARM1, PRMT5), diffuse-large B cell lymphoma (DLBCL) (PRMT5), and B-cell leukemia/lymphoma (PRMT5)." (PMID 39528914, 2024). "Several microRNAs, including miR-19a, miR-25, miR-32, miR-92b, and miR-96, have been identified to bind to the 3′-untranslated region (3′UTR) of PRMT5 mRNA and inhibit PRMT5 translation in lymphoid cancer cells." (PMID 37173967, 2023). "Protein arginine methyltransferase 5 (PRMT5) is a type II PRMT enzyme that is directly involved in the pathogenesis of multiple different lymphomas through the transcriptional regulation of relevant oncogenes." (PMID 36819050, 2023).
lymphoma (continued). "To evaluate the anti-lymphoma efficacy of the combination treatment in vivo, we choose a CDX model derived from ATM-deficient Granta-519 and treated the mice with inhibitors of PRMT5, and ATR, alone or together." (PMID 36797243, 2023). "In lymphoma cells, PRMT5 activates the WNT/β-catenin and AKT/GSK3β signaling pathways and regulates target gene expression." (PMID 36765032, 2023). "The overlap of the highly depleted genes in the T0 control between the two independent screens, confirmed that PRMT5 is one of the few genes identified in our CRISPR screens as essential for lymphoma and clinically actionable." (PMID 36167829, 2022). "The lymphoma cells resistant to the PRMT5 inhibitor were those that evaded successful MSI2 shRNA-mediated knockdown." (PMID 36167829, 2022). "In summary, our study provides data for the role of the PRMT5/MSI2 axis in regulating the key lymphoma drivers, c-MYC and BCL-2." (PMID 36167829, 2022). "PRMT5 is overexpressed in germinal center-derived lymphomas and mantle cell lymphoma and plays an important role in lymphomagenesis by regulating several oncogenic pathways." (PMID 36167829, 2022). "Inhibition of the protein arginine methyltransferase PRMT5 has been suggested as a promising therapy for lymphoma." (PMID 36167829, 2022). "As proliferating lymphoma cells rely on increased translation, knock-out of PRMT5 doubled the lifespan of Eμ-Myc mice." (PMID 35008680, 2021). "Together these findings demonstrate the multifaceted role of PRMT5 in regulating the growth and survival of lymphoma cells." (PMID 33989303, 2021). "To validate these findings, we evaluated the effects of PRMT5 inhibition on primary canine lymphoma samples after 24, 48, and 96 hours." (PMID 33989303, 2021). "PRMT5 inhibitors have shown significant activity in pre-clinical models of Epstein Barr virus (EBV +) lymphomas, DLBCL, and MCL." (PMID 34193230, 2021). "We performed ATAC-sequencing and gene expression microarrays with pathway enrichment analysis to characterize genome-wide changes in chromatin accessibility and whole-transcriptome changes in canine lymphoma cells lines upon PRMT5 inhibition." (PMID 33989303, 2021). "In our studies, the PRMT5 inhibition in primary canine lymphoma samples and cell lines showed significant anti-tumor effects." (PMID 33989303, 2021). "Here, we have assessed the expression of PRMT5 in a large sample of histopathologically distinct subtypes of canine lymphoma." (PMID 33989303, 2021). "Given the oncogenic role of MYC in lymphomagenesis and an established PRMT5/MYC axis in human cancer, we sought to validate the functionality of the PRMT5/MYC axis in canine lymphoma." (PMID 33989303, 2021). "EBV-induced lymphomas and transformed cell lines exhibit abundant expression of PRMT5 critical to EBV-driven B-cell transformation and maintenance of the malignant phenotype." (PMID 33989303, 2021). "To assess expression profiles of PRMT5 in canine lymphomas, we performed immunohistochemistry on canine lymphoma tissue micro arrays (TMAs)." (PMID 33989303, 2021). "Here we report changes in chromatin state and whole-transcriptome profiles showing commonalities and distinctions between human and canine lymphomas coordinated by aberrant PRMT5 expression." (PMID 33989303, 2021). "Taken together, our data supports the continued use of the spontaneous canine lymphoma model to study the oncogenic role of PRMT5 and further develop PRMT5 inhibitors for the treatment of lymphoma." (PMID 33989303, 2021). "Similar to human lymphoma, the three cell lines tested showed a range of sensitivity to PRMT5 inhibition." (PMID 33989303, 2021). "PRMT5 is upregulated in various malignancies including lymphoma with preclinical data supporting the use of PRMT5 inhibitors in DLBCL and other B-cell NHLs." (PMID 34945817, 2021).